RPH3A (rabphilin 3A)
Description:
Plays an essential role in docking and fusion steps of regulated exocytosis (By similarity). At the presynaptic level, RPH3A is recruited by RAB3A to the synaptic vesicle membrane in a GTP-dependent manner where it modulates synaptic vesicle trafficking and calcium-triggered neurotransmitter release (By similarity). In the post-synaptic compartment, forms a ternary complex with GRIN2A and DLG4 and regulates NMDA receptor stability. Also plays a role in the exocytosis of arginine vasopressin hormone (By similarity).
Synonyms: KIAA0985; rabphilin; exophilin-1
Tractability: Antibody: UniProt places it where antibodies can reach, with medium confidence; its Gene Ontology location is reachable by antibodies, with medium confidence. PROTAC: UniProt records ubiquitination sites on it; its protein half-life has been measured.
Gene: Protein-coding gene on chromosome 12 (112,570,380 to 112,898,881, forward strand). Ensembl gene ENSG00000089169.
Subcellular location: Cytoplasmic vesicle, secretory vesicle, synaptic vesicle membrane; Cell projection, dendritic spine; Postsynaptic cell membrane; Membrane
Gene Ontology:
Molecular function: protein binding; calcium ion binding; calcium-dependent phospholipid binding; inositol 1,4,5 trisphosphate binding; phosphate ion binding; phosphatidylinositol phosphate binding; phosphatidylinositol-4,5-bisphosphate binding; protein-containing complex binding; selenium binding; zinc ion binding; small GTPase binding
Biological process: calcium-dependent activation of synaptic vesicle fusion; positive regulation of calcium ion-dependent exocytosis; intracellular protein transport; synaptic vesicle priming
Cellular component: extrinsic component of membrane; extrinsic component of synaptic vesicle membrane; membrane; neuron projection; postsynaptic membrane; protein-containing complex; secretory granule; synapse; synaptic vesicle; synaptic vesicle membrane; dendritic spine
Genetic constraint (gnomAD): Loss-of-function variants: 45 observed, 90.29 expected, observed/expected ratio (o/e) 0.5, 90% interval 0.39 to 0.64. The upper end of that interval is the gene's LOEUF score, 0.64, which puts it in group 2 of 6, group 1 being the genes least tolerant of losing a copy. Missense variants: 745 observed, 878.78 expected, observed/expected ratio (o/e) 0.85, 90% interval 0.8 to 0.9. Synonymous variants: 294 observed, 314.15 expected, observed/expected ratio (o/e) 0.94, 90% interval 0.85 to 1.03.
Homologues: Orthologues: chimpanzee RPH3A (99% identical), macaque RPH3A (99% identical), pig RPH3A (94% identical), dog RPH3A (91% identical), rat Rph3a (88% identical), mouse Rph3a (88% identical), rabbit RPH3A (87% identical), guinea pig RPH3A (77% identical), tropical clawed frog rph3a (72% identical), zebrafish rph3ab (57% identical), zebrafish rph3aa (14% identical). Paralogues in human: DOC2B (36% identical), DOC2A (31% identical), SYTL5 (22% identical), SYTL4 (19% identical), SYT3 (19% identical), SYT6 (19% identical), SYTL2 (18% identical), SYT7 (18% identical), SYT10 (18% identical), SYT1 (17% identical), RPH3AL (16% identical), SYT2 (16% identical), and 19 more.